CRP (C-reactive protein)
Diseases named in the same sentence as CRP in open-access papers (continued):
Sharing a sentence is not in itself a finding about the gene and the disease.
bronchiectasis (47 papers, 2013 to 2026). Segmental, irreversible dilation of the bronchial tree resulting in the accumulation of secretions which leads to obstruction. "In this single center prospective study, elevated serum hs-CRP level at stable-state was found to be associated with increased risks of bronchiectasis exacerbation." (PMID 38350918, 2024). "Univariate regression analysis showed that higher hs-CRP was associated with significantly higher risk of any bronchiectasis exacerbation with odds ratio (OR) of 2.597 (95% confidence interval [CI] = 1.188–5.676, p = 0.017)." (PMID 38350918, 2024). "The CRP value was associated with a greater risk of future severe exacerbations but not with mild or moderate exacerbations in patients with steady-state bronchiectasis from the Spanish Registry of Bronchiectasis (RIBRON)." (PMID 38350918, 2024). "Systemic inflammation, characterized by elevated bloodneutrophil levels, increased CRP, and plasma cytokines, has beenreported in patients with bronchiectasis and is associated withdisease severity." (PMID 38676590, 2024). "This is in support of the role of chronic low-grade inflammation in bronchiectasis, which is reflected by hs-CRP level, in association with bronchiectasis exacerbation risk." (PMID 38350918, 2024). "The optimal cut-off of hs-CRP in longer term bronchiectasis exacerbation risk and mortality are worth exploring in future longer follow-up study especially in a larger population." (PMID 38350918, 2024). "Baseline serum hs-CRP level at stable-state can predict risk of bronchiectasis exacerbation, which is reflecting chronic low-grade inflammation in bronchiectasis." (PMID 38350918, 2024). "In this study, we aim to assess the association between hs-CRP level and the risks of bronchiectasis exacerbation." (PMID 38350918, 2024). "Increasing evidence also showed that PLT and CRP be associated with disease severity, exacerbations and worse clinical outcomes in bronchiectasis." (PMID 38408986, 2024). "This is consistent with our finding that the degree of chronic inflammation at stable-state in bronchiectasis as measured by hs-CRP is associated with the exacerbation risks." (PMID 38350918, 2024). "The level of baseline hs-CRP may possibly reflect the degree of low-grade chronic inflammation in bronchiectasis which eventually be translated into exacerbation risk." (PMID 38350918, 2024). "Elevation of systemic inflammatory markers including C-reactive protein (CRP) and total white cell count, has been found to correlate with the extent of the disease and poor lung function in bronchiectasis." (PMID 38350918, 2024). "hs-CRP level was positively correlated with the number of bronchiectasis exacerbation with r = 0.334, p < 0.001." (PMID 38350918, 2024). "The findings from our study suggest the possible role of hs-CRP as a marker of low-grade systemic inflammation in stable-state that predicts subsequent bronchiectasis exacerbation." (PMID 38350918, 2024). "Baseline serum hs-CRP level at stable-state can predict bronchiectasis exacerbation in the subsequent year." (PMID 38350918, 2024). "In a study involving 87 patients, significant relationshipswere reported between systemic inflammation assessed withleukocyte count, CRP, and erythrocyte sedimentation rate analyses,and the severity of bronchiectasis." (PMID 38676590, 2024). "Hs-CRP was also shown to be able to predict bronchiectasis exacerbation when it is measured as a continuous variable and as categorical variable with a cut-off value." (PMID 38350918, 2024). "A study from Spain demonstrated CRP levels in stable bronchiectasis was a predictive factor for future severe exacerbations of bronchiectasis patients, with higher CRP levels associated with an increased risk of severe exacerbations." (PMID 38191360, 2024). "The level of CRP, as one of the inflammatory markers, was higher on admission of male patients with bronchiectasis than that of females in all patients." (PMID 36772864, 2023).
bronchiectasis (continued). "In conclusion, we found that male patients with bronchiectasis had poorer lung function, higher CRP level, and higher hospital costs than female patients." (PMID 36772864, 2023). "We found a significant correlation (OR=0.9662; 95% C.I =0.2187- 1.8286; p <0.001) between an increased level of CRP and the presence of bronchiectasis (38 in GP 2 vs. 25 in GP1)." (PMID 37273954, 2022). "The significant variables associated with the presence of bronchiectasis found in our study include FEV1, mMRC, sputum purulence, length of hospital stay, QSGR, C-reactive protein, and exacerbations in the previous year." (PMID 37273954, 2022). "NLR and C-reactive protein (CRP) levels were measured in patients with bronchiectasis exacerbation and in healthy controls." (PMID 32944447, 2020). "Antibiotic treatment for 7 days is given to all patients with CRP ≥ 50 mg/l, those with a known diagnosis of bronchiectasis, or those presenting with Anthonisen type I exacerbation." (PMID 31842993, 2019). "Previous studies have found that systemic inflammatory markers such as C reactive protein and airway cytokines (tumor necrosis factor-α, IL-1, IL-8) are increased in patients with bronchiectasis." (PMID 30717716, 2019). "In patients with bronchiectasis, CRP can be a useful biomarker that directly reflects the level of systemic inflammation." (PMID 29270068, 2017). "Additional studies are required to elucidate the clinical significance of the role of CRP in the assessment of treatment response and progression of bronchiectasis after anti-inflammatory therapy." (PMID 29270068, 2017). "BMI was negatively correlated with acute exacerbations, C-reactive protein,erythrocyte sedimentation rate, radiographic extent of bronchiectasis, and chroniccolonization by P. aeruginosa and positively correlated withpulmonary function indices." (PMID 26176309, 2015). "Additionally, the BE-FAO group had higher bronchiectasis severity, more extensive emphysema, worse airway symptoms, higher CRP levels, lower lung function indices, and greater reliance on bronchodilators than the BE group." (PMID 39143556, 2024). "Patients with hs-CRP > 0.35 had significantly more bronchiectasis exacerbation than those with hs-CRP ≤ 0.35, with mean number of exacerbations being 0.54 ± 0.78 in the high hs-CRP group and 0.16 ± 0.43 in the low hs-CRP group, p = 0.001 in both univariate and multivariate analysis." (PMID 38350918, 2024). "Patients with hs-CRP > 0.35 had significantly more bronchiectasis exacerbation than those with hs-CRP ≤ 0.35, with mean number of exacerbations being 0.29 ± 0.67 in the high hs-CRP group and 0.03 ± 0.18 in the low hs-CRP group, p = 0.001 in univariate analysis and 0.015 in multivariate analysis." (PMID 38350918, 2024). "Hs-CRP also has the advantage over CRP that it can detect low-grade inflammation, which may be present in chronic inflammatory conditions such as bronchiectasis." (PMID 38350918, 2024). "It is worthwhile to assess the correlation of hs-CRP with these markers, as well as whether these markers can also predict bronchiectasis exacerbation risks." (PMID 38350918, 2024). "Moreover, in non‐CF bronchiectasis, a positive correlation has been observed between CRP and the high‐resolution computed tomography (HRCT) score." (PMID 37324924, 2023). "However, a previous study showed that bronchiectasis severity scores exhibit a correlation with C-reactive protein levels (FEV1% predicted: 55.5±21.2)." (PMID 33886789, 2021). "C-reactive protein has been evaluated in patients with stable bronchiectasis." (PMID 32944447, 2020). "The mean CRP levels in patients with bronchiectasis exacerbation were 75.03±73.87 mg/l." (PMID 32944447, 2020). "The NLR values were compared to CRP levels in patients with bronchiectasis exacerbation." (PMID 32944447, 2020). "Patients with bronchiectasis and elevated CRP levels showed rapid FEV1 declines in another study." (PMID 29270068, 2017).
bronchiectasis (continued). "The mechanisms by which chronic PA infection influences HRQL are unclear; however, bronchiectasis patients with chronic PA infection exhibit higher cytokine production, which may have contributed to the higher CRP values observed in the current study." (PMID 29237500, 2017). "In the present study, disease severity was correlated with hs-CRP in stable bronchiectasis, demonstrating that hs-CRP may be a good biomarker in low-grade systemic inflammation in such patients." (PMID 24381758, 2013). "A study concluded that CRP value was also associated with a greater risk of future severe exacerbations but not with mild/moderate exacerbations in steady-state bronchiectasis patients, while another study revealed a positive correlation between hsCRP and stable non-cystic fibrosis bronchiectasis." (PMID 37873776, 2023). "The diagnosis of bronchiectasis should be more efficient in patients with COPD having a severe respiratory deficit, purulent sputum, accelerated CRP, and deterioration in the quality of life." (PMID 37273954, 2022). "The diagnosis of bronchiectasis should be more efficient in patients with COPD with a severe respiratory deficit, purulent sputum, accelerated CRP, and deterioration in the quality of life." (PMID 37273954, 2022). "In the present study, the severity of bronchiectasis was assessed based on the recently developed FACED and BSI scoring systems, while systemic inflammation was evaluated by CRP levels, leukocyte count, and N/L ratio." (PMID 29270068, 2017). "In patients with stable bronchiectasis who are evaluated based on FACED and BSI scores, CRP can be a useful biomarker as a direct indicator of the severity of systemic inflammation." (PMID 29270068, 2017). "The severity of bronchiectasis as determined based on BSI and FACED increased significantly with increasing levels of CRP in patients with stable bronchiectasis (p=0.001 and p=0.027, resp)." (PMID 29270068, 2017). "A study assessing the severity of bronchiectasis based on HRCT score reported a significant correlation between HRCT score and markers of systemic inflammation such as WBC and CRP." (PMID 29270068, 2017). "Systemic inflammatory markers, including CRP and fibrinogen, were significantly elevated in COPD patients with bronchiectasis (14.9 vs 11.5, 3.74 vs 3.43, respectively, P < 0.05 for both)." (PMID 27442646, 2016). "Interestingly, we have found a unique subgroup (cluster 3) consisting predominantly of male patients with fever, high levels of CRP and BVAS, and a higher prevalence of bronchiectasis." (PMID 38062524, 2023). "A. Ben Saad conducted a retrospective study on 423 cases of COPD, of which 84 had bronchiectasis, and no CRP difference in the two groups with or without bronchiectasis was reported." (PMID 37273954, 2022). "Neither CRP nor neutrophil count correlated with the microbial species in patients with bronchiectasis (P > 0.05)." (PMID 35346147, 2022). "The NLR values in patients with bronchiectasis exacerbation had no linear correlation with CRP values in these patients (r=0.002, p=0.992)." (PMID 32944447, 2020). "In our study, there was no linear correlation between NLR and CRP values in patients with bronchiectasis exacerbation." (PMID 32944447, 2020). "When the patients were classified as those with mild, moderate, and severe bronchiectasis according to BSI and FACED scores, significant relations were found between FVC%, FEV1%, FEV1/FVC, CRP, BMI, number of exacerbations, and number of hospitalizations according to both scoring systems." (PMID 29270068, 2017). "The relation between CRP or total white blood cell count and the novel scoring systems used to assess bronchiectasis severity, namely, BSI and FACED, has not been investigated before." (PMID 29270068, 2017).
bronchiectasis (continued). "Finally, in children with bronchiectasis, sTREM-1 sputum levels correlated with markers of neutrophilic inflammation but not necessarily with CRP concentrations, suggesting that sTREM-1 may be more sensitive in detecting pulmonary neutrophilic inflammation than CRP." (PMID 27846213, 2016). "Levels of CRP (not hs-CRP) have been shown to significantly correlate with HRCT bronchiectasis scores; however, a very poor correlation with lung function measures has also been reported." (PMID 24381758, 2013). "Both the C-reactive protein level and erythrocyte sedimentation rate have known value asmarkers of systemic inflammation and are indirect markers of disease activity andquality of life for patients with non-CF bronchiectasis." (PMID 26176309, 2015).
fibrosis (47 papers, 2013 to 2026). the formation of excess fibrous connective tissue in an organ or tissue in a reparative or reactive process. "The factors associated with SLD were anthropometric data, glucose, hydroxychloroquine, and C3 levels; meanwhile, anthropometric data, triglycerides, high-density lipoprotein, low-density lipoprotein, C4 levels, and C-reactive protein levels were associated with fibrosis." (PMID 38902318, 2024). "Its expression positively correlated with triglycerides, low-density lipoprotein cholesterol, white blood cell count, CRP, Fibrosis-4, and oxidative stress markers (OA, PA), but negatively with HDL cholesterol." (PMID 41846477, 2025). "The hemoglobin, albumin, lymphocyte, and platelet score was significantly and negatively correlated with C-reactive protein, aspartate, alanine transaminase, gamma glutamyl transferase, aspartate to platelet ratio index, and Fibrosis-4 values." (PMID 38294124, 2024). "In our study, we demonstrated that in the group of patients with fibrosis, patients have associated higher serum values of the LDH, CRP, and lymphocyte count." (PMID 38256314, 2023). "EDA-FN plasma levels resulted significantly correlated with the degree of BM fibrosis (Kruskal-Wallis test, P=0.006) and with the plasma levels of the inflammatory marker high sensitivity-C reactive protein (hs-CRP) (r=0.26; P=0.012)." (PMID 36212480, 2022). "Similarly, a low-sugar diet combined with time-restricted eating (16:8) led to significant reductions in fibrosis, liver enzymes, plasma triglycerides, cholesterol, and CRP after 3-mo." (PMID 39842721, 2025). "Among pre-BS factors that may predict outcomes post-BS, those that have been found to be significant from the adipose tissue are VAT/SAT fibrosis, circulating CRP, Cd11b and IL10 adipose tissue mRNA levels, and possibly circulating leptin." (PMID 33670215, 2021). "Conversely, CRP and LDH were shown to increase within two weeks but then sharply decrease to normal levels in the non-fibrosis group." (PMID 40733571, 2025). "3-, and 1.3-fold lower, but the CRP was 2.6-fold higher in those with fibrosis compared to those without fibrosis (p = 0.01 for IFN-γ; p = 0.09 for IFN-α2; p = 0.04 for MCP-3; p < 0.001 for CRP)." (PMID 33133104, 2020). "These interrelationships may however not explain the profiles of CRP and fibrinogen in the present study populations—as fibrosis parameters and platelet count (a good measure of chronic liver disease stage)—were not measured." (PMID 30540839, 2018). "In contrast to the IL-6 and VCAM-1 results, CRP, TNFα, MCP-1, MIP-1β, and eotaxin levels did not change with fibrosis severity." (PMID 31291245, 2019). "Several biomarkers such as CRP, MPO-ANCA, and KL-6, BVAS, and PFT findings were not different between survivors and non-survivors of MPO-ANCA positive MPA-ILD, whereas bilateral lower lobe fibrosis scores were significantly higher in the non-survivors." (PMID 33452394, 2021).
parasitemia (47 papers, 2007 to 2026). "In our pilot study, we observed increased levels of serum CRP that coincided with peak parasitemia, indicating that P. fragile exposure is linked with increased systemic inflammation." (PMID 39066199, 2024). "Among the children with pathogenic parasitic infections, 6/31 (19.4%) had raised CRP and 11/31 (35.5%) were anaemic." (PMID 28441968, 2017). "CRP was also associated to parasitemia in the multivariate analysis." (PMID 30080904, 2018). "Stepwise logistic regression analysis showed four independent variables to be significantly associated with a diagnosis of bacterial/parasitic infection: emergency physician suspicion, C-reactive protein over 40 mg/l, neutrophil leucocytes over 7,500/mm3, and PCT over 0.2 μg/l." (PMID 17521430, 2007). "Hyperbilirubinemia, the most common abnormality, correlated positively with CRP and the level of parasitemia, and negatively with antibody levels." (PMID 40817086, 2025). "There were moderate to strong correlations between the level of parasitemia and bilirubin (ρ = 0.517), CRP (ρ = 0.444), and the HES (ρ = 0.348) (P < 0.001 each)." (PMID 40817086, 2025). "This trend has been seen in previous studies as well; CRP is produced in response to malaria infection and tends to be elevated in patients with parasitemia." (PMID 38241274, 2024). "The CRP was significantly elevated in bacterial infections compared to viral or parasitic infections." (PMID 38983994, 2024). "B. gibsoni also induces a sudden rise in CRP, which coincides with the appearance of the peripheral parasitemia in experimental infections (which is very delayed compared to similar experimental infections with other parasite species)." (PMID 38133320, 2023). "Similar cytokine profiles were described in two experimentally B. gibsoni-infected dogs but, as with CRP, the onset of increases coincided with the very delayed onset of parasitemia." (PMID 38133320, 2023). "ROC analysis showed that CRP levels were positively correlated with positive cultures and Plasmodium parasitemia." (PMID 37478118, 2023). "Our data shows that C-reactive protein concentrations were increased at the peak of asexual parasitemia compared to baseline (mean 24.0 mg/L ± 4.7 vs 1.3 mg/L ± 0.3), but returned to normal during gametocytemia (3.7 mg/L ± 1.6) and at day 64 (3.1 mg/L ± 2.3)." (PMID 35839244, 2022). "Children living in the community with asymptomatic parasitemia had lower levels of hepcidin, ferritin, CRP and sTfR and lower parasite densities than hospitalized children." (PMID 34498446, 2022). "Patients with increased CRP levels had more than an eight-fold likelihood for parasitemia after correction for other parameters (adjusted OR 8.7 [CI 2.5–30.5], p<0.001)." (PMID 30080904, 2018). "Patients with an increased CRP level had more than an eight-fold likelihood for positive parasitemia (adjusted OR 8.7 [CI 2.5–30.5], p<0.001) in the adjusted multivariable model." (PMID 30080904, 2018). "Some of the differentially abundant proteins such as SAA, CRP, Titin, Apo E exhibited gradual alterations in their serum abundances with an increase in parasitemia." (PMID 28667326, 2017). "High IgG1 galactosylation levels correlated with low total IgE levels, low C-reactive protein levels and low prevalence of parasitic infections." (PMID 27306703, 2016). "Other biomarkers that are involved in parasitic infections include high-sensitivity CRP, procalcitonin, Presepsin, Interleukin-6, N-Outstation Pro-B Type Natriuretic Peptide, soluble urokinase-type plasminogen activator receptor, pancreatic stone protein, CD64, and CD11b." (PMID 40277833, 2025). "Additionally, the correlation analysis showed strong negative correlations between CRP and level of antibodies as well as strong positive correlations between CRP and the levels of parasitemia." (PMID 40817086, 2025).